PHB1P1 (PHB1 pseudogene 1)
Synonyms: formerly PHBP1
Gene: Processed pseudogene on chromosome 6 (150,042,546 to 150,043,353, forward strand). Ensembl gene ENSG00000213091.
Diseases named in the same sentence as PHB1P1 in open-access papers:
PHB1P1 is named in the same sentence as 2 diseases in open-access papers, as found by Europe PMC text mining. Sharing a sentence is not in itself a finding about the gene and the disease.
PHB1P1 shares sentences with these, for which no sentence is quoted: esophageal squamous cell carcinoma (2 papers); tumor (2).